ARID4A (AT-rich interaction domain 4A)
Description:
DNA-binding protein which modulates activity of several transcription factors including RB1 (retinoblastoma-associated protein) and AR (androgen receptor) (By similarity). May function as part of an mSin3A repressor complex. Has no intrinsic transcriptional activity (By similarity). Plays a role in the regulation of epigenetic modifications at the PWS/AS imprinting center near the SNRPN promoter, where it might function as part of a complex with RB1 and ARID4B (By similarity). Involved in spermatogenesis, together with ARID4B, where it acts as a transcriptional coactivator for AR and enhances expression of genes required for sperm maturation. Regulates expression of the tight junction protein CLDN3 in the testis, which is important for integrity of the blood-testis barrier (By similarity). Plays a role in myeloid homeostasis where it regulates the histone methylation state of bone marrow cells and expression of various genes involved in hematopoiesis. May function as a leukemia suppressor (By similarity).
Synonyms: RBBP-1; RBBP1; RBP1; RBP-1
Tractability: Antibody: its Gene Ontology location is reachable by antibodies, with high confidence. PROTAC: UniProt records ubiquitination sites on it; ubiquitination databases record sites on it; its protein half-life has been measured.
Target class: Methyl-lysine/arginine binding protein; Reader; Epigenetic regulator; Tudor domain
Safety:
Unwanted effects reported when the protein is acted on. In parentheses: how it was acted on, where the effect was seen, and who reports it.
alcoholism (source: ClinPGx)
Gene: Protein-coding gene on chromosome 14 (58,298,504 to 58,373,887, forward strand). Ensembl gene ENSG00000032219.
Subcellular location: Nucleus
Subcellular location (Human Protein Atlas): Nucleoplasm; Plasma membrane
Pathways (Reactome):
Chromatin organization: HDACs deacetylate histones
Disease: Potential therapeutics for SARS
Gene Ontology:
Molecular function: DNA binding; transcription cis-regulatory region binding; double-stranded DNA binding
Biological process: negative regulation of DNA-templated transcription; negative regulation of cell migration; negative regulation of stem cell population maintenance; negative regulation of transcription by RNA polymerase II; negative regulation of transforming growth factor beta receptor signaling pathway; positive regulation of stem cell population maintenance; regulation of transcription by RNA polymerase II; regulation of DNA-templated transcription
Cellular component: nucleoplasm; nucleus; transcription repressor complex; Sin3-type complex
Genetic constraint (gnomAD): Loss-of-function variants: 25 observed, 103.06 expected, observed/expected ratio (o/e) 0.24, 90% interval 0.18 to 0.34. The upper end of that interval is the gene's LOEUF score, 0.34, which puts it in group 1 of 6, group 1 being the genes least tolerant of losing a copy. Missense variants: 1,016 observed, 1,167.2 expected, observed/expected ratio (o/e) 0.87, 90% interval 0.83 to 0.92. Synonymous variants: 374 observed, 390.37 expected, observed/expected ratio (o/e) 0.96, 90% interval 0.88 to 1.04.
Homologues: Orthologues: chimpanzee ARID4A (99% identical), macaque ARID4A (99% identical), dog ARID4A (94% identical), pig ARID4A (94% identical), rabbit ARID4A (90% identical), mouse Arid4a (86% identical), rat Arid4a (85% identical), tropical clawed frog arid4a (65% identical), zebrafish arid4a (46% identical), Caenorhabditis elegans arid-1 (22% identical), Drosophila melanogaster htk (15% identical). Paralogues in human: ARID4B (45% identical), ARID5B (14% identical), ARID5A (8% identical).
Diseases named in the same sentence as ARID4A in open-access papers:
ARID4A is named in the same sentence as 30 diseases in open-access papers, as found by Europe PMC text mining. Sharing a sentence is not in itself a finding about the gene and the disease. The quoted sentences say what the papers report.
breast carcinoma (6 papers, 1999 to 2025). "Moreover, ‘amplification’ and ‘mutation’ were the two primary alteration frequencies of Arid4a in breast cancer patients." (PMID 40066676, 2025). "Arid4a expression is decreased in human breast tumors and several commonly used cell lines and is strongly related to poor outcomes in breast cancer patients." (PMID 40066676, 2025). "In summary, we revealed the low expression pattern of Arid4a in breast cancer and its inhibitory effect on tumor metastasis progression." (PMID 40066676, 2025). "To test the effect of Arid4a on the progression of breast cancer, we treated established breast tumors with an Arid4a‐expressing adenovirus." (PMID 40066676, 2025). "Arid4a expression is suppressed in human liver cancer tissues and is related to the prognosis of human breast cancer patienrs." (PMID 40066676, 2025). "Here, we identified the low expression pattern of RNA‐binding protein Arid4a in human breast cancers and its potential role in modulating tumor metastasis‐related gene expression and tumor progression." (PMID 40066676, 2025). "Overall, these results demonstrate that a reduction in Arid4a decreased the mRNA stability of metastasis‐suppressing genes and promoted the progression of breast cancer metastasis." (PMID 40066676, 2025). "Together, these data revealed that reduced Arid4a expression was closely correlated with severely poor prognosis in breast cancer patients." (PMID 40066676, 2025). "ARID4A is a tumor suppressor in breast cancer, the expression of which indicates better OS in patients with breast cancer." (PMID 36034939, 2022). "Moreover, the expression of metastasis‐suppressing genes, including MTSS1, TIMP2, Rb1, and PTEN, gradually increased with increasing Arid4a expression in human breast cancer samples." (PMID 40066676, 2025). "Notably, Arid4a has been reported to participate in regulating the metastasis process of multiple cancers, including breast cancer, thyroid cancer and lung cancer." (PMID 40066676, 2025). "Low Arid4a expression was significantly correlated with poor prognosis in breast cancer patients." (PMID 40066676, 2025). "Overall, our results reveal that Arid4a inhibits breast tumor metastasis by increasing the expression of metastasis‐suppressing genes through stabilizing mRNAs, which provides a potential target for breast cancer treatment." (PMID 40066676, 2025). "Since Arid4a expression significantly correlates with nodal metastasis in human breast cancer, we next detected whether Arid4a affects the migration and invasion of breast tumor cells." (PMID 40066676, 2025). "In contrast to the study, ARID4A was a lower expression in breast cancer tissues than normal tissues, its mRNA expression foreboded better OS in breast cancer patients, peculiarly in luminal A and basal-like type breast cancer, so we spectated ARID4A as a tumor suppressor in breast cancer." (PMID 33592583, 2021). "Arid4a was confirmed to suppress breast tumor metastasis progression by stabilizing the transcripts of tumor metastasis–suppressing genes, suggesting that Arid4a might be a potential therapeutic target for breast cancer treatment." (PMID 40066676, 2025). "Therefore, our findings showed that Arid4a, as a metastasis suppressor, might be a promising therapeutic target for breast cancer." (PMID 40066676, 2025). "Notably, we noted that there was a significant correlation between Arid4a expression and nodal metastasis in breast cancer, which implied that Arid4a might be a predictive biomarker of breast tumor metastasis progression." (PMID 40066676, 2025).
breast carcinoma (continued). "Furthermore, we found that Arid4a expression gradually decreased with increasing breast cancer pathological stage and nodal metastasis, suggesting that Arid4a expression might be involved in breast tumor metastasis." (PMID 40066676, 2025). "Arid4a expression was also decreased in our breast tumor samples and different subtypes of breast cancer, including luminal, HER2+, and triple‐negative breast tumors." (PMID 40066676, 2025). "Low mRNA expression of ARID2 (p=0.0035), ARID4A (p=0.0349), JARID1A (p=0.0473), JARID1D (p=0.0322) and high mRNA expression of JARID1B (p=0.0067), JARID1C (p=0.0407) were interrelated with worse OS in grade II breast cancer patients." (PMID 33592583, 2021). "However, a peptide epitope equal to ARID4A (KASIFLK), which preferentially expresses in breast cancer cell lines and tissues, maybe indicates ARID4A as a tumor oncogene." (PMID 33592583, 2021). "In addition, Kaplan–Meier plotting revealed that lower Arid4a expression predicted poor overall survival (OS), relapse‐free survival (RFS), distant metastasis‐free survival (DMFS), disease‐free survival (DFS), and disease‐specific survival (DSS) of patients with breast cancer." (PMID 40066676, 2025). "The low mRNA expression of ARID1B (p=0.0023), ARID2 (p=0.0439), ARID4A (p=0.0056), ARID4B (p=0.0317), ARID5B (p=0.00054), JARID1D (p=0.043), JARID2 (p=0.0068) were interrelated with poor survival in breast cancer patients with negative lymph node." (PMID 33592583, 2021). "The expression of ARID1A, ARID1B, ARID2, ARID3A, ARID4A, and ARID4B in no-luminal subtypes was lower than luminal subtypes, however, ARID3C, ARID5A, and JARID2 mRNA expression were higher in no-luminal subtypes of breast cancer tissues." (PMID 33592583, 2021).
prostate carcinoma (4 papers, 2021 to 2025). A carcinoma that arises from epithelial cells of the prostate gland. "Down-regulation of ARID4A directly regulated by microRNA-30d promoted tumor progression and in patients with prostate cancer." (PMID 33592583, 2021). "In patients with prostate cancer, the down-regulation of ARID4A promotes tumor progression." (PMID 36034939, 2022). "miR-30d promotes prostate cancer progression by targeting both ARID4A and ARID4B23." (PMID 33824274, 2021). "In prostate cancer, miR-30d binds to the 3′ UTR of ARID4A and ARID4B, resulting in the downregulation of these molecules and enhanced cancer progression." (PMID 40558499, 2025). "Altogether, the co-downregulation of ARID4A and ARID4B could serve as a prognostic biomarker in prostate cancer patients." (PMID 40558499, 2025).
gastric cancer (2 papers, 2017 to 2021). A primary or metastatic malignant neoplasm involving the stomach. "It was illustrated that miR-376c-3p augments the anchorage-independent growth of gastric cancer cells via repressing AT-rich interactive domain-containing protein 4A (ARID4A, also called RBP-1), which negatively regulates E2F-mediated transcription." (PMID 33435156, 2021). "Our results demonstrate that miR-376c functions by suppressing ARID4A expression, which in turn enhances the oncogenicity of gastric carcinoma cells." (PMID 28486502, 2017).
leukemia (2 papers, 2020). A malignant (clonal) hematologic disorder, involving hematopoietic stem cells and characterized by the presence of primitive or atypical myeloid or lymphoid cells in the bone marrow and the blood. "ARID4A has been considered a tumor suppressor gene because it is frequently mutated or weakly expressed in breast, oral, tongue, and colorectal cancers and leukemia." (PMID 33585230, 2020).
liver cancer (2 papers, 2019 to 2022). An epithelial or non-epithelial malignant neoplasm that arises from the liver. "While ARID4A is not described in COSMIC or previous sequencing studies of liver cancer, recurrent mutations in the paralogous nucleosome remodelers ARID1A, ARID1B, and ARID2 have been previously reported in HCC21,30,35." (PMID 31796844, 2019).
acute myeloid leukemia (1 paper, 2025). Acute myeloid leukemia (AML) is a group of neoplasms arising from precursor cells committed to the myeloid cell-line differentiation. "Furthermore, a haplo-deficiency of Arid4b in adult mice promoted the development of acute myeloid leukemia in Arid4a null mice." (PMID 40558499, 2025). "A deficiency of Arid4a in mice follows a series of clinical conditions that are similar in humans, like defective hematopoiesis, chronic myelomonocytic leukemia (CMML)-like myelodysplastic/myeloproliferative disorder, and its final transformation into acute myeloid leukemia (AML)." (PMID 40558499, 2025).
bone marrow failure (1 paper, 2010). "These mice also show bone marrow failure with myelofibrosis and higher frequencies of hematologic malignancies, providing evidence that ARID4A functions as a tumor suppressor gene and its absence is permissive for the proliferation of connective tissue elements." (PMID 20441585, 2010).
breast tumor (1 paper, 2025). "Bioinformatic analysis, qRT–PCR, immunohistochemistry, and immunoblotting were employed to determine the expression of Arid4a in breast tumor tissues and its association with the survival of cancer patients." (PMID 40066676, 2025). "Given that Arid4a can inhibit the migration and invasion of breast tumor cells, we next identified the metastasis‐associated genes affected by Arid4a using the Human Tumor Metastasis RT2 Profiler PCR Array (QIAGEN)." (PMID 40066676, 2025). "Overall, these findings suggest that the ARID domain of Arid4a is important for mediating breast tumor metastasis and is associated with tumor progression." (PMID 40066676, 2025). "Moreover, the positive correlation between the expression levels of Arid4a and metastasis‐suppressing genes in human breast tumors further suggests an association between Arid4a and metastasis suppression." (PMID 40066676, 2025). "Together, these findings indicate that Arid4a stabilizes metastasis‐suppressing mRNAs through targeting the 3′ UTR in breast tumor cells." (PMID 40066676, 2025). "Exogenous expression of Arid4a effectively inhibited breast tumor cell proliferation, migration, and invasion, whereas silencing Arid4a expression promoted breast tumor metastasis." (PMID 40066676, 2025). "Arid4a functions as a ‘switch’ of tumor metastasis by mediating the balance of metastasis‐promoting and metastasis‐suppressing genes in human breast tumor cells." (PMID 40066676, 2025). "In vitro and in vivo cellular experiments were used to assess the function of Arid4a in breast tumor metastasis." (PMID 40066676, 2025). "The half‐lives of metastasis‐suppressing mRNAs, including MTSS1, TIMP2, RB1, and PTEN, were prolonged by approximately 1‐fold in Arid4a‐overexpressing breast tumor cells." (PMID 40066676, 2025). "Taken together, these results clearly indicate that Arid4a can inhibit breast tumor cell proliferation, migration, and invasion in vitro." (PMID 40066676, 2025). "In this study, we revealed that the expression of Arid4a is impaired in human breast tumor tissues and strongly correlates with patient prognosis." (PMID 40066676, 2025). "The Arid4a expression pattern in human breast tumors was first examined by surveying different TCGA databases." (PMID 40066676, 2025). "We also found that Arid4a expression was decreased in several commonly used breast tumor cell lines." (PMID 40066676, 2025). "The reduced Arid4a expression was further confirmed by evaluating the extent of Arid4a immunohistochemistry (IHC) staining in breast tumor tissues." (PMID 40066676, 2025). "Arid4a overexpression effectively inhibits breast tumor growth and metastasis both in vitro and in vivo." (PMID 40066676, 2025). "Reduced expression of Arid4a in breast tumor samples was detected via bioinformatic analyses and experimental methods." (PMID 40066676, 2025). "All four metastasis‐promoting gene mRNAs were decreased in Arid4a‐overexpressing cells, and all the metastasis‐suppressing genes increased upon Arid4a overexpression in breast tumor cells." (PMID 40066676, 2025). "We demonstrated the inhibitory roles of Arid4a in regulating the proliferation, cell cycle progression, migration, and invasion of breast tumor cells." (PMID 40066676, 2025). "Here, we revealed that Arid4a selectively upregulated the expression of metastasis‐suppressing genes, thereby inhibiting breast tumor metastasis." (PMID 40066676, 2025). "Corresponding to the overexpression results, we next examined the effects of Arid4a knockdown on breast tumor metastasis." (PMID 40066676, 2025). "We first found that silencing Arid4a expression promoted breast tumor cell proliferation and activity." (PMID 40066676, 2025). "Currently, few studies have investigated the effects of Arid4a on the behavior of breast tumor cells." (PMID 40066676, 2025).
breast tumor (continued). "MTSS1, TIMP2, RB1, and PTEN were selected as targets of Arid4a in breast tumor cells for further study for two main reasons: (i) they are among the genes most highly regulated by Arid4a in breast tumor cells; and (ii) they are known typical metastasis inhibitory genes." (PMID 40066676, 2025). "Furthermore, our IHC results confirmed that the expression of MTSS1 is greater in human breast tumor tissues highly expressing Arid4a." (PMID 40066676, 2025). "We further found that Arid4a can induce cell cycle arrest in breast tumor cells." (PMID 40066676, 2025). "Notably, the expression of Arid4a and metastasis‐suppressing genes was positively correlated in human breast tumor tissues." (PMID 40066676, 2025). "Moreover, in vivo administration of Arid4a‐expressing adenovirus inhibited breast tumor progression." (PMID 40066676, 2025). "Relatively low expression of Arid4a in primary breast tumors was detected." (PMID 40066676, 2025). "The western blotting results confirmed the knockdown of Arid4a in breast tumor cells." (PMID 40066676, 2025). "In addition, lower Arid4a protein expression was observed in primary breast tumors and various subtypes of breast tumors." (PMID 40066676, 2025). "Notably, the expression of metastasis‐suppressing genes, including MTSS1, TIMP2, Rb1, and PTEN, was increased according to the expression of Arid4a in breast tumor tissues." (PMID 40066676, 2025). "In addition, we observed that MTSS1 expression was increased by Arid4a over time in breast tumor cells." (PMID 40066676, 2025). "As expected, silencing Arid4a significantly promoted the migration of breast tumor cells in vitro." (PMID 40066676, 2025). "However, the mechanism by which Arid4a affects human breast tumor cell metastasis is still unclear." (PMID 40066676, 2025). "In addition, the induction of Arid4a in vivo inhibits the growth and metastasis of breast tumors." (PMID 40066676, 2025). "Indeed, Arid4a overexpression effectively inhibited breast tumor cell migration and invasion." (PMID 40066676, 2025). "Thus, Arid4a might suppress breast tumor metastasis by inhibiting the tumor angiogenesis pathway, which would require further study." (PMID 40066676, 2025). "Besides, the half‐lives of metastasis‐suppressing mRNAs are prolonged by Arid4a, indicating for the first time that Arid4a stabilizes the metastasis‐suppressing transcripts through targeting the 3′ UTR in human breast tumor cells." (PMID 40066676, 2025). "However, how Arid4a regulates breast tumor metastasis has not been reported." (PMID 40066676, 2025).
endometrial cancer (1 paper, 2020). Primary or metastatic malignant neoplasm involving the endometrium (mucous membrane that lines the endometrial cavity). "However, disregarding the impact of target therapies for ovarian and endometrial cancer, there is no direct link between ARID4A and female fertility." (PMID 32408659, 2020).
epilepsy (1 paper, 2025). A brain disorder characterized by episodes of abnormally increased neuronal discharge resulting in transient episodes of sensory or motor neurological dysfunction, or psychic dysfunction. "For example, APBB2 was reported to be associated with aging, ZNF608 with preclinical AD, ARID4A and ARVCF with neuropsychiatric diseases, CNN3 with epilepsy, and BTBD1O with ALS." (PMID 40725187, 2025).
hypogonadism (1 paper, 2023). A disorder characterized by decreased function of the gonads. "Mice lacking arid4a and arid4b (Arid4a(−/−) and Arid4b(+/−)) exhibit the progressive loss of male fertility with hypogonadism and spermatophore hypoplasia." (PMID 37254055, 2023).